SIRT6 (sirtuin 6)
Diseases named in the same sentence as SIRT6 in open-access papers (continued):
Sharing a sentence is not in itself a finding about the gene and the disease.
tumor (continued). "As the function of SIRT6 in tumour suppression was controversial, we first tried to prove the relationship between SIRT6 and NSCLC using a meta‐analysis." (PMID 39224032, 2024). "Deacetylase Sirtuin family member 6 (SIRT6) exhibits anti-tumor properties and plays a critical role in regulating metabolic processes and enhancing AEG in tumor cells." (PMID 39906672, 2024). "Consistent with the results in GEPIA2.0, the mRNA expression of PARP2 and SIRT6 was significantly increased in HCC tissues compared to that in non-tumor tissues." (PMID 39408693, 2024). "Sirtuins, such as SIRT1, SIRT2, and SIRT6, interact with crucial signaling pathways, influencing tumor metabolism, genomic stability, and the progression of ADM." (PMID 39682281, 2024). "Among these, three studies reported higher SIRT6 expression in NSCLC tissues than in tumour‐adjacent tissues, whereas the other four studies reported opposite results." (PMID 39224032, 2024). "In contrast, SIRT6 can suppress aerobic glycolysis in tumor cells to inhibit cell growth and the cancerization of embryonic fibroblasts." (PMID 39408693, 2024). "This regulation influences not only tumor cell survival but also the recruitment of immune cells, such as macrophages and neutrophils, positioning SIRT6 as a critical component of the cancer-immune interface." (PMID 39796040, 2024). "Based on Gene Expression Profiling Interactive Analysis 2.0 (GEPIA2.0), PARP2 and SIRT6 were significantly upregulated in HCC tissues compared to those in non-tumor tissues." (PMID 39408693, 2024). "Histone deacetylase SIRT6 is a tumor suppressor that controls cancer metabolism and inhibits cancer metabolism." (PMID 39588377, 2024). "In contrast, six genes known to inhibit cell proliferation and tumor growth were overexpressed in d-HGP: SIRT6, MPC2, MIR4458HG, ST20-AS1, SREBF2, MRPL40." (PMID 38548918, 2024). "In line with our expectations, NSC232003 treatment was more efficient in suppressing SIRT6-low PDX tumors than those derived from SIRT6-high PDXs, as quantified by tumor growth curves." (PMID 39709438, 2024). "Some targets, such as DLX4, NDRG3, WNT1, MYC, CREB1, and SIRT6, are involved in tumor or cell proliferation." (PMID 39618816, 2024). "SIRT6 exerts a protective effect against tumor growth, enhances programmed cell death, and inhibits cellular proliferation in lung, colorectal, and ovarian cancers." (PMID 39479446, 2024). "In contrast, SIRT6 acts as a tumor suppressor by repressing glycolysis and maintaining chromatin stability, with its loss leading to increased metabolic dysregulation and genomic instability, driving tumor growth." (PMID 39682281, 2024). "Specifically, epigenetic mechanisms represented by m6A, NcRNA and some key regulatory proteins, such as GPX4, CD71, ETV4 and SIRT6, interfere with TC progression by regulating tumour cell ferroptosis." (PMID 39163517, 2024). "The data indicated that the tumor incidence of Sirt6 Floxed mice and Sirt6-LKO mice reached 91% (11/12) and 100% (12/12), respectively (Fig. EV5C)." (PMID 38332150, 2024). "Sirtuins, acting as tumor suppressors, include sirtuin 6 (SIRT6), which is overexpressed in NSCLC cell lines." (PMID 39204314, 2024). "SIRT3 and SIRT4 suppress oncogenic pathways by regulating cancer metabolism, while SIRT2 and SIRT6 influence tumor aggressiveness and androgen receptor sensitivity, with SIRT6 promoting metastatic potential." (PMID 39796040, 2024). "Our results have also shown that Sirt6 is a tumor suppressor in the liver, as Sirt6-LKO mice spontaneously developed tumors at two years old." (PMID 38332150, 2024). "SIRT6 exhibits dual roles as a tumor suppressor or oncogene, depending on the specific cancer tissue or cell type." (PMID 38819446, 2024). "By means of the JAK2/STAT3 signaling pathway, SIRT6 can inhibit tumor cell growth by inducing apoptosis and diminishing oxidative stress." (PMID 39408693, 2024).
tumor (continued). "This novel KLF10/SIRT6 signaling pathway presents promising therapeutic potential by ameliorating tumor metastasis through the coordinated regulation of metabolic and migratory processes." (PMID 39682281, 2024). "SIRT6 is dysregulated in various cancers, and its role in tumorigenesis depends on the type and context of the tumor." (PMID 38548549, 2024). "The role of SIRT6 in tumours is double‐edged sword‐like, exerting promotional and inhibitory effects in different tumour types." (PMID 39163517, 2024). "As expected, the tumor growth curve suggested that the UMUC-3 cells with SIRT6-KD formed larger tumors than the control cells." (PMID 39709438, 2024). "In HCC tissues, the mRNA and protein levels of PARP2 and SIRT6 were significantly higher than those of non-tumor tissues (p < 0.001)." (PMID 39408693, 2024). "Several studies have confirmed Sirt6 as both an oncogenic factor and a tumor suppressor in some cancers." (PMID 38172884, 2024). "CircITCH, a tumor-suppressive circRNA, attenuated doxorubicin-induced cardiotoxicity by the miRNA-330-5p/SIRT6 axis and improved streptozotocin-induced diabetic renal fibrosis through the miRNA-33a-5p/SIRT6 axis." (PMID 37191431, 2023). "A metabolic shift towards glycolysis known as the Warburg effect, which is crucial for maintaining fast tumor development, was also shown to be mediated by SIRT6." (PMID 38203666, 2023). "Increasing the SIRT6 expression or targeting the anti-apoptotic function of survivin at the cancer initiation stage noticeably impairs tumor development." (PMID 38203666, 2023). "After an initial delay in the tumor onset, SIRT6-OE induces a more aggressive phenotype of Delta16HER2 tumors promoting the formation of higher number of tumor foci and metastases than controls." (PMID 38081972, 2023). "Hepatocellular, ovarian, lung, and breast cancers present decreased levels of SIRT6 and increased tumor progression." (PMID 37630770, 2023). "For example, sirtuin 6 (SIRT6) is a tumor suppressor that inhibits HIF-1α and, as a consequence, reduces HK, LDHA and GLUT1." (PMID 37345199, 2023). "Consistently, SIRT6-OE maintains the majority of Delta16HER2/SIRT6-OE tumor cells in G0/1 phase, while Delta16HER2 tumors show G2/M accumulation typical of highly proliferating tumors." (PMID 38081972, 2023). "They discovered that SIRT6 influences tumor-initiating cells (TICs), which are responsible for tumor formation and growth." (PMID 37629689, 2023). "SIRT6 can act as a tumor suppressor intervening in DNA repair, genomic maintenance, cell metabolism and directly co-repressing several tumor-promoting genes." (PMID 38081972, 2023). "D25N, A89S, D116N, and E260Stop mutants display less of a tumor suppression effect than the WT SIRT6 in a xenograft mouse model." (PMID 36831330, 2023). "This review presents the current knowledge on SIRT6, a member of the sirtuin family, and it aims to summarize the role of SIRT6 in carcinogenesis and tumor development." (PMID 38203666, 2023). "Perhaps, SIRT6 expression is often downregulated in early tumor formation contributing to the increased genomic instability and pro-tumor reprogramming." (PMID 38081972, 2023). "The deletion of SIRT6 in vivo increases the number, growth, and aggressiveness of tumors and SIRT6 expression can predict patients’ survival, indicating that SIRT6 acts as a potent tumor suppressor that inhibits cancer metabolism." (PMID 38203666, 2023). "This evidence indicates that SIRT6 protects cancer cells from the oxidative DNA damage during tumor progression." (PMID 38081972, 2023). "Research performed on colorectal, breast, ovarian, hepatic, lung, and other malignancies discovered the correlation between SIRT6 expression, tumor growth, and clinical outcome." (PMID 38203666, 2023). "We observed a significant increase in CD44 and OCT3/4 levels in Delta16HER2/SIRT6-OE tumor bulk over Delta16HER2 both in terms of median fluorescence intensity (MFI), and population frequency." (PMID 38081972, 2023).
tumor (continued). "The overexpression of SIRT6 possesses oncogenic effects and favors the development and progression of tumor cells and thus has become a target for epigenetic therapy." (PMID 38235110, 2023). "More importantly, this study demonstrated that small molecule SIRT6 inhibitors promote antitumor drug sensitivity in vivo tumor models for the first time." (PMID 37542062, 2023). "The histone deacetylase sirtuin 6 (SIRT6) has been endowed with anti-cancer capabilities in many tumor types." (PMID 38081972, 2023). "As an inhibitor of aerobic glycolysis, crucial for the growth of cancer cells, SIRT6 acts as a tumor suppressive factor." (PMID 37630770, 2023). "This phenotype of SIRT6-OE tumors is associated with cancer stem cell (CSC)-like features and tumor dormancy, and low senescence and oxidative DNA damage." (PMID 38081972, 2023). "Eventually, they silenced SIRT6 by engineered exosomes that delivered siRNA to efficiently suppress tumor growth and metastasis on xenografted tumor models of mice." (PMID 37008065, 2023). "Among the seven sirtuins, SIRT6 is a chromatin-binding protein with diverse roles in genome stability, glucose metabolism, tumor suppression, and the organismal lifespan." (PMID 36982232, 2023). "In NSCLC cell lines and tumor tissues, SIRT6 is proved to be upregulated, and statistical analyses showed that high SIRT6-expressing NSCLC patients had a lower cumulative survival rate as compared with low SIRT6-expression patients." (PMID 35172823, 2022). "Conversely, a study recently demonstrated that SIRT6 acts as a tumor promoter, given that its expression promoted MCF-7 cell growth as well as resistance to oxidative stress." (PMID 36291902, 2022). "Particular attention is paid to studies illustrating the critical role of SIRT6 in the regulation of immune cells from the viewpoints of immunesenescence, immunometabolism, and tumor immunology." (PMID 35463332, 2022). "Further, upregulated SIRT6 achieves the function of tumor suppression in HCC through inhibiting phosphorylation of ERK1/2 and reducing the expression of cycling D1 and p-ERK." (PMID 35172823, 2022). "Here, we briefly summarize the enzymatic characteristics of SIRT6; describe in detail the roles of these biochemical and molecular characteristics in aging, immunity, and cancer; and explore the role of SIRT6 in epigenetic immunity and tumor immunology." (PMID 35463332, 2022). "The action of SIRT6 is reported to be tissue‐specific, and thus, it acts as a tumor suppressor in some cancer types, while, as an oncogene in others." (PMID 35686673, 2022). "In this report, we have indicated for the first time, the involvement of SIRT6 in illustrating the importance of mitochondria to facilitate tumor progression through altered actin dynamics." (PMID 35686673, 2022). "For example, immunohistochemistry revealed that SIRT6 expression was considerably lower in tumour tissues than in normal tissues in RCC patients, implying that SIRT6 worked as a tumour suppressor." (PMID 35172823, 2022). "The current meta-analysis, which included 15 studies and 1577 patients, was the first to summarise all previously published research on the effect of SIRT6 expression on human tumour prognosis." (PMID 35172823, 2022). "Surveys of the genes negatively correlated with SIRT6 in public databases considered SIRT6 as tumor suppressors, which was confirmed by the cell proliferation and migration assays after transient transfection of SIRT6 overexpression vector into AGS cells." (PMID 36324577, 2022). "SIRT6 is a predominant member of the sirtuin family having implications for tumor metabolism and progression." (PMID 35686673, 2022).
tumor (continued). "Elevated SIRT6 expression leads to tumor cell apoptosis by upregulating the expression of Bax and cleaved caspase-8, and downregulating Bcl-2, and inhibiting the Janus kinase 2 (JAK2)-STAT3 pathway." (PMID 35463332, 2022). "SIRT6, one of the core members of the sirtuin family, is considered to act as a double-edged sword in cancer, with dual roles as a tumor suppressor and oncogene." (PMID 35915188, 2022). "SIRT6 expression was significantly different in 11 different types of malignant tumours compared to normal tissues (P < 0.05)." (PMID 35172823, 2022). "SIRT6 serves as a tumor suppressor and is observed decreased in various cancers such as colorectal, hepatocellular and pancreatic cancers." (PMID 35715817, 2022). "SIRT6, a key member of the long-lived protein family, has been shown to regulate a variety of physiological processes and is intimately involved in tumour formation and progression." (PMID 35172823, 2022). "To confirm these results, we knocked-down Pdk1 in APC; Sirt6IECΔ organoids and saw reduced organoid formation and growth, further supporting the involvement of glucose metabolism in Sirt6-driven tumor initiation." (PMID 35314684, 2022). "Characteristics such as neoplastic cell maintenance and tumor growth have been well documented in these cases, especially in studies with SIRT6 in correlation with pathways such as AMPK." (PMID 36230534, 2022). "The current study demonstrated that SIRT6 acts as a double-edged sword during the development of solid tumours, suppressing or promoting tumour growth, depending on the type of tumour." (PMID 35172823, 2022). "In pancreatic cancer, SIRT6 expression was distinctly decreased and its overexpression suppressed tumor metastasis." (PMID 35251169, 2022). "These tumour cells are syngeneic to the C57BL6 background of the SIRT6 over‐expressing and littermate mice used in this study." (PMID 34212132, 2021). "In the cancer cachexia model that we used, muscle‐specific SIRT6 over‐expression was able to reduce the tumour burden in the mice." (PMID 34212132, 2021). "In gastrointestinal tumors, SIRT6 was reported to have tumor-suppressive effects thanks to its ability to prevent HIF-1α and NF-κB activity." (PMID 33482921, 2021). "The analysis of different databases, such as the Cancer Cell Line Encyclopedia, reveals that SIRT6 expression is suppressed in several types of cancer, suggesting a tumor suppressor role for this enzyme." (PMID 33800266, 2021). "SIRT6 acts as a tumor suppressor by promoting DNA repair and genome stability, glucose homeostasis, etc.." (PMID 33920726, 2021). "The tumor sections were processed to detect immunofluorescence staining with an anti-Survivin antibody, and the results indicated cell apoptosis rate in SIRT6-knockdown group was increased." (PMID 33995674, 2021). "SIRT6 has been demonstrated as a tumour‐suppressor and is shown to antagonize tumorigenesis by modulating multiple pathways." (PMID 34212132, 2021). "We then tested the effect of inhibition of SIRT6 by using the aptamer-modified exosomes carrying the SIRT6 siRNA in subcutaneously and orthotopically xenografted tumor models." (PMID 33995674, 2021). "It has been reported that SIRT6 serves as either a tumor suppressor gene or an oncogene as it can inhibit tumor formation by improving genomic stability and induce tumor progression by promoting genomic instability." (PMID 34927546, 2021). "Mounting evidence points towards a double-faced involvement of SIRT6 in tumor onset and progression since the block or induction of apoptosis lead to opposite outcomes in cancer." (PMID 33800266, 2021). "Several factors regulate SIRT6 expression and activity at transcriptional and post-transcriptional level, influencing its role on tumor initiation and progression." (PMID 33800266, 2021). "Conversely, SIRT6 over‐expression in tumour‐bearing mice significantly down‐regulated plasma FFA levels." (PMID 34212132, 2021).
tumor (continued). "We evaluated the effect of a heterozygous deletion of Sirt6 on tumor latency and survival of mouse mammary tumor virus (MMTV)-PyMT mice." (PMID 33482921, 2021). "Silencing SIRT6 also reduced the growth of C42B as assessed by tumor sphere assays and immunofluorescence staining of Ki67." (PMID 33995674, 2021). "SIRT6 over‐expression significantly reduced myostatin expression and plasma free fatty acids levels but maintained plasma insulin levels in tumour‐bearing mice." (PMID 34212132, 2021). "As a tumor suppressor, SIRT6 is down-regulated in colorectal, ovarian, breast, lung, pancreatic, and hepatocellular tumors." (PMID 34650436, 2021). "In a liver cancer mouse model SIRT6 has a tumor suppression effect, repressing the transcription of survivin at two levels: through H3K9 deacetylation at its promoter and through NF-κB deacetylation, which impairs its binding to survivin promoter." (PMID 33800266, 2021). "We also examined Sirt6 mRNA and protein levels in gastrocnemius muscle samples of tumour‐bearing mice." (PMID 34212132, 2021). "Decreased respiratory complex activity and ATP/AMP ratio were also detected in healthy, non-tumor-bearing mammary glands from Sirt6+/− mice as compared to the glands from Sirt6+/+ animals." (PMID 33482921, 2021). "Through this action, SIRT6 exerts a tumor suppressor role as it blocks the so-called Warburg effect." (PMID 33800266, 2021). "Together this provides a model where SIRT6 acts as a tumor suppressor by inhibiting R-Ras2 and downregulating proliferative PI3K/Akt signaling." (PMID 34368168, 2021). "In BC patients, high tumor levels of SIRT6 were shown to enhance BC cell resistance to chemotherapeutics and to promote BC survival, migration, and invasion through the expression of cyclin D1, NF-κB, β-catenin, and matrix metalloproteinase 9 (MMP9)." (PMID 33482921, 2021). "SIRT6 has previously been shown to function in tumor suppression by reprogramming multiple gene expression pathways through histone deacetylation." (PMID 34573442, 2021). "While there was no significant change in WNT4 protein expression in gastrocnemius muscle of N.Tu‐CN and N.Tu‐Sk.T6Tg mice, in tumour‐bearing mice, SIRT6 over‐expression significantly reduced its expression in the muscle." (PMID 34212132, 2021). "Among these, the role of SIRT6 in DNA damage repair has suggested a role for SIRT6 as a tumor suppressor." (PMID 34359939, 2021). "qRT-PCR was utilized to quantify SIRT6 expression in clinical samples, which showed lower SIRT6 expression in cancer tissues than in adjacent non-tumor tissues." (PMID 33510943, 2021). "SIRT6 over‐expression not only helped in preserving the muscle weight, but it also significantly reduced tumour volume and tumour weight." (PMID 34212132, 2021). "Using A549 cells as NSCLC, it has been reported that miR-34a works as a tumor suppressor by targeting SIRT6." (PMID 34944497, 2021). "Our mouse cytokine array analyses showed that SIRT6 over‐expression in the skeletal muscle significantly inhibited plasma levels of CXCL10 in the tumour‐bearing mice." (PMID 34212132, 2021). "The SIRT6 interfering efficiency in orthotopic transplantation tumor models was confirmed by immunohistochemistry." (PMID 33995674, 2021). "Overall, our results indicated that SIRT6 over‐expression in skeletal muscle not only reduced tumour progression but also blocked cancer‐induced muscle degeneration." (PMID 34212132, 2021). "Other cytokines that consistently showed significant inhibition by muscle‐specific SIRT6 over‐expression in tumour settings were IL‐1α and IL‐16." (PMID 34212132, 2021). "Mice carrying the heterozygous Sirt6 deletion exhibited a marked increase in tumor latency and a consistent increase in their overall survival." (PMID 33482921, 2021). "The heterozygous Sirt6 deletion extended tumor latency and mouse survival in the MMTV-PyMT mouse BC model, while SIRT6 silencing slowed the growth of MDA-MB-231 BC cell xenografts." (PMID 33482921, 2021).